KRAS (KRas proto-oncogene, GTPase)
Diseases named in the same sentence as KRAS in open-access papers (continued):
Sharing a sentence is not in itself a finding about the gene and the disease.
lung cancer (continued). "Another study reported that mitochondrial ROS are necessary for the KRAS (Kirsten rat sarcoma virus)—induced anchored-independent growth of lung cancer." (PMID 37597078, 2023). "The role of TBK1 in Kras-mediated tumor development is significant as it inhibits cell apoptosis, particularly in human lung cancer cell lines, and is dependent on the expression of carcinogenic KRAS." (PMID 37781382, 2023). "We have also reported that EGFR/KRAS activation drives BH4 production in lung cancer and that blocking EGFR signaling reduces BH4." (PMID 37251335, 2023). "KRAS mutations in NSCLC are more frequent (about 30% of cases) than EGFR mutations (15%), which is in agreement with smoking frequency in lung cancer patients." (PMID 36817482, 2023). "For example, in pancreatic and lung cancer, it has been reported that oncogenic KRAS mutants stimulate the transcription of NRF2 via JUN and MYC." (PMID 37373496, 2023). "In KRAS-mutant lung cancer patients, M2 macrophages, MDSCs, CD4+FoxP3+ Treg cells, IL-17-producing T helper cells displayed a pro-tumorigenic TME." (PMID 36874015, 2023). "The interaction proteomics screen was complemented by a dual CRISPR knockout screen targeting 7021 pairs of 119 genes in two mutant KRAS lung cancer cell lines." (PMID 36607281, 2023). "In a similar approach to the previous ones described, the authors generated LKB1−/− KRAS -driven lung cancer cells and assembled them as spheroids." (PMID 38106674, 2023). "The double knockout compromised the viability of KRAS-dependent lung cancer cells in vitro and in in vivo xenografts." (PMID 36607281, 2023). "Next, we analysed the RNA expression levels of the TGFβ target genes p21, PAI1, SMAD7, and TGFB1 following SHP099 treatment in KRAS mutant lung cancer cell lines." (PMID 38102334, 2023). "Together, these studies identify two promising therapeutic strategies for KRAS-mutant NSCLCs and reveal important insights into the biological consequences of targeting the eIF4F complex in lung cancer." (PMID 37384411, 2023). "In the lung cancer model, KRAS G12V induced tumor cells to secrete IL-10 and TGF-β1 by activating the MEK-ERK-AP1 pathway to induce Tregs infiltration." (PMID 37670322, 2023). "Research has shown that knocking down CSNK2A1 in KRAS (G12C) mutant lung cancer cells reduced cell proliferation, inhibited Wnt/β-catenin signaling, and enhanced the anti-proliferative effects of MEK inhibitors on KRAS (G12C) mutant lung cancer cells." (PMID 38155968, 2023). "Despite these challenges, KRAS-G12C inhibitors have demonstrated clinical benefit and are likely to be useful as second-line treatments for lung cancer." (PMID 37662925, 2023). "These functions, which would be expected to limit cellular proliferation, are consistent with the proliferation-driving effects of Setd2 inactivation in KRAS-driven lung cancer." (PMID 36899051, 2023). "To assess the impact of UHRF1 loss on DNA methylation in KRAS mutant lung cancer cells, we depleted UHRF1 or KRAS using siRNA in two KRAS-driven cell lines (H358 and A549) and analyzed changes in DNA methylation." (PMID 37407562, 2023).
lung cancer (continued). "Further insights into KRAS-mutant lung cancers and other cancers have revealed their dependence on MET for anchorage-independent growth in 3-D conditions but not monolayer conditions." (PMID 37381723, 2023). "Recently, the integration of Tuba-seq into CRISPR-mediated multiplexed screens revealed that HRAS and NRAS presented a suppressive effect on KRAS-driven lung cancer growth in vivo." (PMID 38188023, 2023). "In this single-group phase-2 trial, patients pre-treated (previous platinum-based therapy and/or anti-PDL1 therapy) for KRAS G12C mutant lung cancer received second-/third-line sotorasib, with a primary endpoint of objective response (OR)." (PMID 38067288, 2023). "Patients with concurrent mutations in KRAS and KEAP1/NFE2L2 had a shorter duration of therapy with platinum-based chemotherapy than other patients with KRAS-mutant lung cancer." (PMID 37345046, 2023). "The role of CRAF in mediating tumor growth in KRAS mutant lung cancer, pancreatic cancer, and colon cancers is gradually gaining consensus in the scientific community." (PMID 38111008, 2023). "In line with this, here we show that genetic ablation of UHRF1 in combination with pharmacological inhibition of KRAS G12C, MEK, or PI3K results in a synergistically anti-proliferative effect in KRAS mutant lung cancer cells in vitro." (PMID 37407562, 2023). "At the initial stage of KRAS-driven lung cancer, NK cells can exhibit strong cytotoxic effects and secrete cytotoxic factors to kill target cells directly." (PMID 37108242, 2023). "Traditionally, chemotherapy has been used for patients with KRAS-mutant lung cancer and other solid tumors." (PMID 36675641, 2023). "Clinical trials demonstrated that KRAS wild-type lung cancer patients exhibited better responses to chemotherapy than KRAS mutant patients; however, the difference was not significant." (PMID 37509464, 2023). "CHD3 instead is a member of the NuRD complex, and it also supports viability of KRAS-mutant lung cancer cell lines." (PMID 36858798, 2023). "GRP78 haploinsufficiency is reported to inhibit KRAS G12D-mediated tumor progression and prolong survival, and it is a potential therapeutic target for KRAS-mutant lung cancer." (PMID 36675641, 2023). "The effect of the combination of 10-Hydroxycamptothecin (HCPT) and crizotinib (CRI) on EGFR- and KRAS-mutant lung cancer cells was investigated and the conjugates of the two drugs were synthesised." (PMID 36305251, 2023). "In another work, long-term administration of antioxidants, vitamin E, and N-acetylcysteine has been shown to promote KRAS-mediated lung cancer metastasis." (PMID 37597078, 2023). "Collectively, these results suggest that SHP2 inhibition induces TGFβ signalling in KRAS mutant lung cancer models." (PMID 38102334, 2023). "To further establish the clinical relevance of the synthetic lethality of DEX in LKB1-mutant lung cancer, we chose a NSCLC PDX adenocarcinoma (LTL-657) from a bank of NSCLC PDXs based on high expression of CPS1 and somatic mutations of KRAS and LKB1." (PMID 37035141, 2023). "The resulting glutamate-deficient state in lung cancers that bear KEAP1 mutations was also highlighted in another study that employed a KRAS-driven lung cancer model." (PMID 36509429, 2023). "Collectively, we for the first time investigated the effect of the combination of HCPT and CRI on EGFR- and KRAS-mutant lung cancer cells and first synthesised the conjugates of the two drugs." (PMID 36305251, 2023). "The effect of de novo lipogenesis on lipid remodeling has also been studied using KRAS-mutant lung cancer cells after fatty acid synthase (FASN) inhibition." (PMID 37612411, 2023). "Knockdown of NOP56 in KRAS-mutant lung cancer cell lines significantly increased reactive oxygen species (ROS) in KRAS-mutant cell lines, resulting in significantly higher levels of apoptosis in KRAS-mutant cell lines than in controls." (PMID 36741964, 2023).
lung cancer (continued). "Miriam Molina-Arcas from the Crick Institute in London, Great Britain, talked about the impact of the KRAS oncogene signaling on the TME with focus on lung cancer, KRAS as the most common driver oncogene with a frequency of 32% in this disease." (PMID 37347257, 2023). "We, therefore, sought to determine if SHP2 inhibitors enhanced TGFβ signalling in KRAS mutant lung cancer models." (PMID 38102334, 2023). "Aside from direct inhibitors of KRAS G12C, other approaches aimed at treating these mutant lung cancers via downstream regulation are under investigation." (PMID 38067288, 2023). "It was also highly predictive across an external dataset of lung cancer lines treated with KRAS G12C inhibition." (PMID 37141389, 2023). "Despite the success of KRAS G12C inhibitors in non–small cell lung cancer (NSCLC), more effective treatments are needed." (PMID 37384411, 2023). "Anlotinib, a tyrosine kinase inhibitor, has been shown to exert an anti-cancer effect in vitro on KRAS mutant lung cancer cells by inhibiting the MEK/ERK pathway." (PMID 38067288, 2023). "Meanwhile, AMPKα deletion has been shown to promote KRAS-mediated lung-cancer growth and metastasis." (PMID 37240137, 2023). "Taken together, this study demonstrates that active KRAS can promote innate immune evasion of lung cancer through upregulation of CD47." (PMID 36413402, 2023). "We also established the prognostic value of modules associated with targets of ETV5 transcription factor, translational elongation, G protein-coupled receptor (GPCR) signaling, and ribonucleoprotein (RNP) sub-unit organization in KRAS-mutant lung cancers." (PMID 36950380, 2023). "In the work, of Sayin and his group, diet supplemented with vitamin E and N-acetylcysteine resulted in increased tumor progression and suppressed survival in mouse models of KRAS and BRAF mutations in lung cancer." (PMID 37597078, 2023). "In the lung cancer dataset, the highest AUC was detected for miR-17-5p microRNA, followed by KRAS and CD274 (PD-L1)." (PMID 37568797, 2023). "In this study, we reasoned that miRNA-based combination therapy represents an attractive therapeutic strategy to increase cisplatin response of KRAS-driven lung cancer." (PMID 37704611, 2023). "Mutational activation of KRAS is frequently observed in pancreatic cancer, CRC, and non–small cell lung cancer." (PMID 37020035, 2023). "Based on our siRNA screening results, RNF168 inhibition resulted in significant inhibition of cell viability across all three tested KRAS-mutant lung cancer cell lines." (PMID 36858798, 2023). "Using CRISPR/Tuba-seq, a study of 48 TSGs characterizes the functional landscape of tumor suppression in an KRAS-driven lung cancer model, revealing novel genetics of KRAS-driven lung cancer initiation, overall and abnormal growth." (PMID 38169973, 2023). "While further experimentation is essential to establish their functional roles, some of these modules, such as GPCR signaling, open up potentially novel avenues for therapeutic targeting in KRAS-driven lung cancers." (PMID 36950380, 2023). "In contrast to that in KRAS-mutant lung cancer cells, the increase in total lipids in prostate cancer cells was not due to an increase in fatty acid uptake because similar lipidomic changes were observed under serum-free conditions." (PMID 37612411, 2023). "Luteolin and its derivative apigenin are reported to significantly suppress the expression of PD-L1 induced by IFN-γ, leading to the better anti-tumor activity of KRAS-mutant lung cancer, and a synergistic effect combined with PD-1 ICIs." (PMID 36675641, 2023). "For example, AMF-26 has entered clinical studies for targeting lung cancer with resistance toward KRAS inhibitors." (PMID 37046746, 2023).
lung cancer (continued). "Using an adapted protocol for the growth of tumor organoids, we also tested the drug combination under 3D conditions, since mut KRAS lung cancer cells display a higher dependence on KRAS oncogene signaling in 3D cultures than 2D counterparts." (PMID 37816716, 2023). "An important example of the relationship between oncogenes and mtROS is the KRAS oncogene, which is activated in colorectal cancer, lung cancer, and many others." (PMID 37009472, 2023). "Analysis of a large KRAS mutant LUAD database indicated that this type of lung cancer has increased potency to metastatize to the lung but decreased one to the liver and to invade the pleural surface." (PMID 38239281, 2023). "Studies have shown that overexpression of GATA3 was found in KRAS-driven lung cancer cells and further promoted tumorigenesis through microRNA." (PMID 37924117, 2023). "More research is needed to analyse the relationship between KRAS and EGFR gene mutations in the occurrence of lung cancer." (PMID 37340599, 2023). "Although divergent functions have been reported for LINC00673 in human cancers, our data support an oncogenic role of it in PDAC and lung cancer through regulation of KRAS." (PMID 36241718, 2023). "The prognostic value of ERBB inhibitors in KRAS-mutant lung cancer patients needs further evaluation to confirm the variability of these inhibitors." (PMID 36899885, 2023). "They further showed that patients with KRAS mutations were more likely to develop HPD, presumably because KRAS-driven lung cancer frequently inactivates the STK11 gene, resulting in a poor response to immunotherapy." (PMID 36831655, 2023). "In mouse models of KRAS-driven lung cancer and HER2-driven breast cancer, HK2 was necessary for tumor initiation and maintenance as demonstrated using Hk2 conditional knockout mice." (PMID 37190033, 2023). "Recent report also showed that antioxidants supplementation promoted KRAS-driven lung cancer metastasis." (PMID 36802400, 2023). "To this end, we targeted the selected proteins with five siRNAs per gene, in three KRAS-mutant non–small-cell lung cancer cell lines, A549, H358, and H460." (PMID 36858798, 2023). "Several studies have demonstrated that CRAF plays a crucial role in the development of lung carcinoma driven by the KRAS oncogene." (PMID 38111008, 2023). "For example, the mitogen-activated protein kinase (MAPK) pathway, a downstream pathway of KRAS, plays a central role in the initiation and progression of cancers driven by RAS or RAF mutations, including PDAC, colorectal cancer, lung cancer, and melanoma." (PMID 35727403, 2022).
lung cancer (continued). "Collectively, our results suggest that the MAPK/ERK signaling axis promotes BCL6 expression in KRAS-mutant lung cancer cells." (PMID 36377663, 2022). "Supper activation of KRAS remains a significant obstacle for successful lung cancer treatment in clinic." (PMID 36457047, 2022). "Recently, blocking the MEK/ERK pathway via small molecule inhibitors was shown to effectively inhibit the growth of KRAS-mutant lung cancer and melanoma." (PMID 35614034, 2022). "We reviewed the different treatment approaches, focusing on the novel therapeutic strategies for the treatment of KRAS-mutant lung cancers." (PMID 36012655, 2022). "EFGR-inhibiting drugs suppress the KRAS expression level in A549 lung cancer cells to inhibit cell proliferation." (PMID 36330448, 2022). "Inhibition of FASN by cerulenin blocked proliferation of KRAS-driven lung cancer cells, indicating a promising role of lipid metabolism in tumor treatment." (PMID 35898882, 2022). "We examined the ratioof KRAS:PDE6D in three lung cancer cell linesthat had the highest KRAS levels among the cells analyzed (A549, H358,and H2009), as well as two cell lines with low KRAS levels but seeminglyhigher levels of PDE6D than KRAS (Daoy and Jurkat)." (PMID 35104933, 2022). "Though dissociation of mutant KRAS homodimer results in tumor suppression, blocking heterodimerization between wildtype and mutant KRAS accelerates cancer cell growth in lung cancer models." (PMID 35966590, 2022). "Mice bearing primary KRAS-mutant lung cancer xenografts (LACPDX) were treated with vehicle, etoposide (10 mg/kg body weight), FX1 (5 mg/kg body weight) or both drugs in combination for 24 days." (PMID 35503721, 2022). "Gefitinib and erlotinib inhibit the activation of EGFR-mediated PI3K/Akt/mTOR in A549, A549-gefitinib-resistant, KRAS-mutant H358, and H441 cells, leading to lung cancer cell apoptosis." (PMID 36547898, 2022). "In a clinical trial, patients with KRAS-mutant lung cancer displayed response to abemaciclib, with a safety profile." (PMID 35814226, 2022). "In attempt to have an enhanced therapeutic effect in lung cancer therapy exosomes have been electroporated with KRAS siRNAs and were administered to A549 tumors in vivo, KRAS was knocked down, and the tumor was subsequently suppressed." (PMID 36362424, 2022). "Mutant KRAS (KM), the most common oncogene in lung cancer (LC), regulates fatty acid (FA) metabolism." (PMID 35882862, 2022). "Here, we employed the XTR system to identify processes regulated by LKB1, which is among the most frequently altered tumor suppressors in human lung cancer and one of the most potent suppressors of oncogenic KRAS-driven lung tumor growth." (PMID 35228570, 2022). "Genetic alterations of the PI3K, AKT, PTEN, EGFR, and KRAS genes, MET amplification, and EML4-ALK rearrangements are associated with lung cancer progression." (PMID 36230484, 2022). "More importantly, we developed the precision treatment scheme on transgenic mouse model of autochthonous lung cancer: Combination of pan-KRAS inhibitor, NF-κB inhibitor and PD-1 inhibitor effectively shrank KRAS mutation positive/ZNF24-low lung cancers." (PMID 36457047, 2022). "For lung cancers, lung adenocarcinomas baring mutations in EGFR, KRAS, ERBB2, and MET are reported to also host a higher number of “rearrangements”34." (PMID 35710642, 2022).